ATRX (ATRX chromatin remodeler)
Diseases named in the same sentence as ATRX in open-access papers (continued):
Sharing a sentence is not in itself a finding about the gene and the disease.
tumor (continued). "Furthermore, tumours with the ALT phenotype frequently harbour acquired somatic mutations in the ATRX gene." (PMID 24651726, 2014). "For example, ATRX, a chromatin remodeling gene on the X chromosome, is a putative tumor suppressor of which loss-of-function mutations are strongly correlated with alternative lengthening of telomeres (ALT, a mechanism independent of telomerase activity) in cancers." (PMID 24147068, 2013). "The requirement for ATRX mutations in GBM may thus be due to tumor location and/or the age of the patient." (PMID 22661320, 2012). "Furthermore, tumor size demonstrates predictive value for ATRX/DAXX loss in PanNETs ≥2 cm, highlighting the relationship between tumor morphology and molecular alterations, however, this finding remains hypothesis-generating and requires further validation." (PMID 42199802, 2026). "Furthermore, somatic mutations in genes like EPAS1 (encoding HIF-2α) and ATRX have been implicated in tumor development and aggressiveness, broadening the genetic landscape of PPGLs and highlighting the heterogeneity even within tumor subtypes." (PMID 41597272, 2026). "Given that elevated ROS appeared to be a robust inducer of ALT activity in ATRX-null cells, it was next considered whether any other genetic events which naturally occur concurrently with ATRX mutations in tumours that are frequently ALT-positive might exert their effect via generation of ROS." (PMID 39921567, 2025). "It has been reported that ATRX mutation could promote tumor progression." (PMID 38884081, 2024). "Thus, ATRX plays an important tumor-suppression role in OS, and loss of function of this gene may underlie new therapeutic vulnerabilities." (PMID 36073547, 2022). "Therefore, it indicated that the immune system in NSCLC patient with ATRX mutation maybe more active against cancer cells, which prolonged the control of tumor and bring benefits to the survival of patient." (PMID 33409155, 2020). "Whether ATRX deficiency directly induces G4 formation and DNA damage, however, remains unestablished, as does the impact of G4s on the pathogenesis of ATRX-deficient neoplasia." (PMID 30808951, 2019). "Mutations in the genes DAXX and ATRX, which encodes for two subunits of a chromatin remodelling complex required for H3.3 incorporation at pericentric heterochromatin and telomeres, were identified in 31% of samples overall and in 100% of the tumours with a H3.3 mutation." (PMID 22771539, 2013). "Functioning as a tumor suppressor, ATRX regulates chromatin architecture and mediates critical protein‐DNA interactions essential for genomic stability." (PMID 41317331, 2026).
tumor (continued). "Collectively, copy number losses of critical genes involved in chromatin remodeling, especially SMARCB1 and ATRX, were observed in UTROSCTs with extrauterine metastasis, suggesting an important mechanism for tumor evolution and progression." (PMID 41317331, 2026). "Given the secretion of at least two chemokines known to promote macrophage recruitment in ATRX LoF models, we established xenograft models to examine the tumor microenvironment." (PMID 39892705, 2025). "We demonstrated a striking correlation between loss of the ATRX gene and downregulation of DRG2 expression in tumour types which are frequently ALT-positive, including LGG and HGG." (PMID 39921567, 2025). "Some genes exhibit tumour-type-specific patterns, including BRAF, ATRX, and PTEN, where transcriptional signatures of mutation are strong but limited to specific tumour types." (PMID 40775769, 2025). "In contrast, in the urinary bladder, DAXX and ATRX expression declined with increasing tumour grade (between grades 2 and 3)." (PMID 41472189, 2025). "In contrast, in the bladder, expression of DAXX and ATRX declined with increasing tumour grade (p < 0.05)." (PMID 41472189, 2025). "ATRX showed one of the strongest tumour-type-specific transcriptional patterns in LGG tumours, with DRG2 gene having the highest Gini score." (PMID 40775769, 2025). "The human tumor samples that metabolically resemble fly tumors showed strong enrichment for mutations in IDH1, GTF2I and ATRX." (PMID 40523311, 2025). "A central mechanistic link between ALT and tumor biology lies in ATRX and DAXX, chromatin remodelers critical for the deposition of histone variant H3.3 at telomeric and pericentromeric regions." (PMID 41148828, 2025). "Upon progression, a second partial resection was followed by DNA methylation profiling, which reclassified the tumor as a glioneuronal tumor with ATRX alteration, kinase fusion, and anaplastic features (GTAKA), harboring a KANK1::NTRK2 fusion." (PMID 41397922, 2025). "Co-mutation of SETD2 and ATRX occurs in up to 18% of paediatric HGG and, as such, this finding sheds light on the genetic aetiology of these highly aggressive tumours." (PMID 39921567, 2025). "ATRX protein levels are also significantly elevated in GBM tumor tissues compared to normal controls, supporting the transcriptional data." (PMID 40282990, 2025). "One patient had a PD-L1 combined positive score >20, a high tumor mutational burden, a BRCA1 rearrangement, and an ATRX splice site mutation." (PMID 40377969, 2025). "TERT and ATRX-alterations are associated with metastatic PCPG and these tumours have an increased mutation load, and distinct transcriptional and telomeric features." (PMID 40097403, 2025). "In GBM, ATRX deficiency synergizes with ALT to exacerbate DNA replication stress, making tumor cells more susceptible to spontaneous DNA breaks and reduced proliferative fitness." (PMID 41148828, 2025). "This demonstrated that ATRX-mutant LGG had a significantly higher hypoxia signature score, indicating higher levels of hypoxia in these tumours, which is known to be associated with elevated ROS." (PMID 39921567, 2025). "Biomarkers like DAXX, ATRX, and Ki-67 provide insight into tumor aggressiveness and differentiation." (PMID 39841762, 2025). "Markers included CD4+ (helper T cells), CD8+ (cytotoxic T cells), CD11c+ (dendritic cells), TCRγ/δ+ (γ/δ T cells), ATRX+ (tumour cells) and DAPI+ (nuclei), with STING as a primary marker of interest." (PMID 39856469, 2025).
tumor (continued). "In this study, a nomogram model was developed by integrating tumor immune markers (ATRX, IDH1, Ki-67) and clinical characteristics (age, WHO grade, postoperative radiotherapy and chemotherapy)." (PMID 41008886, 2025). "Functional studies revealed that ATRX-mutated tumours exhibit ALT positivity and loss of ATRX protein expression." (PMID 40831998, 2025). "Although expression levels did not distinguish between non-malignant and malignant bladder tissues, UC showed a reduction in DAXX and ATRX expression with increasing tumour grade." (PMID 41472189, 2025). "Including molecular biomarkers beyond MGMT, like IDH1/2 mutation status, ATRX loss, TERT promoter mutation, EGFR amplification, and 1p/19q co-deletion, can improve the model’s understanding of tumor biology." (PMID 41584616, 2025). "Long non-coding RNAs and pseudogenes were enriched in genes differentially expressed in ATRX-altered tumours (Pearson's Chi-squared p-value=9.9e-14)." (PMID 38978571, 2024). "TERT and ATRX-alterations were associated with metastatic PCPG and these tumours had an increased mutation load, and distinct transcriptional and telomeric features." (PMID 38978571, 2024). "Several false positive tumor cells detected by Var1 and Var5 had a reduced ATRX signal in their nuclei." (PMID 38263411, 2024). "Abundant genetic evidence supports the classification of ATRX as a tumor suppressor in human cancer." (PMID 38272925, 2024). "Several studies have investigated the potential ALT stimulation by inactivation of ATRX in tumor cells, obtaining contrasting results." (PMID 38333682, 2024). "Further, our analysis shows that MEN1, DAXX or ATRX and PTEN mutations commonly co-occur, suggesting that combined loss of those tumor suppressors is likely a key event in pancreatic neuroendocrine cell tumorigenesis." (PMID 38609433, 2024). "Tumor tissue samples were also classified as IDH1-wildtype or IDH1-mutated (n = 19 and n = 22, respectively), ATRX-retained or ATRX-lost (n = 19 and n = 13, respectively), and low- or increased-cell-density (n = 21 and n = 17, respectively)." (PMID 39061219, 2024). "By contrast, ATRX-intact control tumors exhibited uniformly strong ATRX expression in tumor cell nuclei." (PMID 38272925, 2024). "To investigate if SCNAs are linked to increased telomere length in ALT tumors, we tested each chromosome arm for association between tumor DNA content and ALT using logistic regression, controlling for ATRX mutations (STAR methods)." (PMID 39635126, 2024). "ATRX loss led to a significant increase in CD3 + T cells and, in particular, CD4 + T-cells within tumor-bearing hemispheres in allografted mice, while macrophage infiltration was reduced." (PMID 38272925, 2024). "Such neoplasms are also enriched in MEN1 and ATRX/DAXX mutations and can harbor high-TMB as an actionable target." (PMID 39331358, 2024). "The beta-like subtype clearly segregated from the other two subtypes, and demonstrated scarcity of MEN1/ATRX/DAXX mutations, few copy-number events and low tumor stage." (PMID 39456803, 2024). "To test this, we analyzed genomes from a diversity of tumor types with driver mutations in either ATM, MEN1, SETD2, BRCA1, BRCA2 and ATRX." (PMID 38909016, 2024). "Among the myriad factors implicated in tumor initiation and progression, abnormalities in ALT are notable features associated with ATRX dysregulation." (PMID 39479502, 2024).
tumor (continued). "Gene-expression in neoplastic cells was confirmed using the snRNA-seq data and differential expression in ATRX mutant tumours was validated using independent bulk RNA-seq datasets." (PMID 38978571, 2024). "All neoplasms were investigated with immunohistochemistry for neuroendocrine markers (Synaptophysin, Chromogranin-A), ATRX, DAXX, ARX, and PDX1 transcription factors." (PMID 39331358, 2024). "The training cohort used to build the model contains comprehensive clinical information (such as tumor location, resection range, ATRX expression, and MGMT promoter methylation), which helped to create a robust model." (PMID 37340065, 2023). "Given that many proteins have been purported to have a role in fork stability this raises the important question as to why ATRX appears to be the dominant tumour suppressor for ALT cancers?" (PMID 36940725, 2023). "ATRX alterations as well as typical morphological characteristics of isomorphic tumor cells with condensed nuclei and anaplastic features are additional unifying pattern of tumors within this group." (PMID 36933012, 2023). "A critical insight into the tumor suppressor mechanisms of DAXX and ATRX comes from the mutual exclusivity of mutations, suggesting their shared function in tumor suppression." (PMID 37633949, 2023). "One study showed that most high-risk NB tumours have TERT rearrangements, MYCN amplification or ATRX mutations, all of which extend telomere length, suggesting an important role for TMM in clinical prognosis." (PMID 37958407, 2023). "Since the discovery that ATRX is often lost in ALT-(alternative lengthening of telomeres) positive tumours, studies on the molecular mechanism by which ATRX suppresses the ALT pathway in cancer far outnumber those on its roles in development." (PMID 37171606, 2023). "This includes one patient where the biopsy from the primary tumor displayed a larger inversion with a break within ATRX, while later material from the resected tumor showed an intragenic deletion (case 76R4/B)." (PMID 38136279, 2023). "In the investigated cohort, 22 ATRX aberrations were detected in tumor material from 21 patients, as judged from SNP microarrays, MLPA, and/or WGS." (PMID 38136279, 2023). "The mutation landscape of HRR-related genes revealed several possible recurrent hotspot driver mutations in ARID1A, ATRX, ATM, and BRCA1/2, including R1989* in ARID1A, which was carried by over 30 tumor patients." (PMID 37264024, 2023). "ATRX expression was localised in the nucleus of tumour cells but was abundant in the 136 tissues of the TMA, which were defined as ATRX-High group." (PMID 38126976, 2023). "ATRX is an important tumor suppressor in OS, and it is a part of a multiprotein complex that regulates chromatin remodeling, nucleosome assembly, and telomere maintenance." (PMID 37511127, 2023). "In this study, OGM detected MYCN amplification in three cell lines (NB1691, NBLW and SK-N-BE2(C)), a TERT rearrangement in one cell line (GI-ME-N) and an intragenic ATRX deletion in a NB tumour." (PMID 37958407, 2023). "ATRX is ranked by NDSI as the strongest SNA-based tumour suppressor, 9th strongest CNA-based tumour suppressor, 5th strongest mixed (SNA+CNA) tumour suppressor and 9th strongest driver averaged across all classes." (PMID 35975235, 2022). "Other genomic features including ATRX as well as copy number status of chromosomes 1p and 19q serve to molecularly segregate this tumor group." (PMID 35526077, 2022).
tumor (continued). "Among 100 tumor-normal pairs sequenced, somatic mutations of 1p tumor suppressors KIF1Bβ and CHD5 were most frequent (2%) after ALK and ATRX (8%), and BARD1 (3%)." (PMID 35768791, 2022). "The impact of DAXX/ATRX and MEN 1 mutations on tumor biology, methylomes and their association with different phenotypic features, i.e., alternative lengthening of telomeres (ALT) are further detailed in this review." (PMID 36139607, 2022). "The relationship of other clinicopathological features, including tumor grade, histological diagnosis, IDH mutation status, 1p/19q codeletion, TERT promoter status, ATRX status, and MGMT promoter status, with the TrMRS were also given out." (PMID 36386216, 2022). "PLMRS was significantly associated with age at diagnosis, tumor grade, IDH mutational status, 1p19q codeletion status, ATRX mutational status, MGMT promoter methylation status, TERT promoter status and histology, but not gender." (PMID 36203434, 2022). "This suggests that the ATRX-related sensitivity to STATi and BTKi is influenced by other factors such as the cellular genetic background and the cell type from which the tumor originates." (PMID 35406561, 2022). "Samples of P07-aRMS were obtained at the same timepoint but showed different events: the primary tumour exhibited an ATRX-deletion, whilst the metastasis harboured SNVs in ATR and RAF1, a biallelic BCOR-deletion, and a MYCN-amplification." (PMID 36182817, 2022). "As pNENs were the most analyzed tumor in GEP-NEN (epi)genomics, and the genes MEN1, DAXX, and ATRX are the most frequently mutated in pNENs, we investigated their mutational status across racial groups via IHC analyses." (PMID 36969744, 2022). "Specifically, analysis of extensive tumor collections confirmed the prevalence of three key mutational driver types in HR-NB, namely MYCN amplification, ATRX inactivation, and rearrangement of the TERT promoter." (PMID 36030273, 2022). "In a recent clonal analysis of tumor samples, the amplification of MYCN occurs in ~ 20 to 30%, ATRX mutations or deletions in ~ 10%, TERT mutations in ~ 10%, and MDM2-CDK mutations in ~ 2% of HR-NB." (PMID 36030273, 2022). "The PuMRS high-risk group significantly had higher tumor grade, more TERT promoter mutation, less IDH mutation, less 1p/19q codeletion, less MGMT promoter methylation, and less ATRX mutation." (PMID 36438805, 2022). "ATRX is a 300 Kbp-long tumour suppressor that lies at the long arm of X chromosome in position 21.1, composed of 36 exons that encode a 280 kDa full-length protein." (PMID 36010860, 2022). "ATRX immunoreactivity was retained; however, residual tumor progressed in size 7 years later and appeared under histology as GBM with loss of ATRX expression." (PMID 36147920, 2022). "miR-1269a can significantly down-regulate the expression of ATRX in vivo and in vitro, and the overexpression of ATRX can also reverse the tumor-promoting effect induced by miR-1269a." (PMID 35252180, 2022). "Consistent with the results of the shRNA-mediated knockdown study, ATRX KO increased both the rate of tumor growth and final tumor volume as compared with WT 143B cells." (PMID 36073547, 2022).